B4GALT1 (beta-1,4-galactosyltransferase 1)
Diseases named in the same sentence as B4GALT1 in open-access papers (continued):
Sharing a sentence is not in itself a finding about the gene and the disease.
pancreatic cancer (4 papers, 2022 to 2025). "A high expression of B4GALT1 in tumors was associated with a poor prognosis in patients with pancreatic cancer, and B4GALT1 overexpression promoted cell migration and invasion." (PMID 37907465, 2023). "In this study, we identified compound 1105486 as the first selective small-molecule inhibitor of β-1,4-galactosyltransferase 1 (B4GALT1) through transcriptomics-guided target discovery and structure-based virtual screening, and validated its in vitro efficacy in pancreatic cancer models." (PMID 40860122, 2025). "Experimental studies further confirm that silencing or knocking down B4GALT1 in PDAC cell lines leads to marked reductions in cell proliferation, migration, and invasive capacity, thus establishing its crucial role in pancreatic tumor progression." (PMID 40860122, 2025). "Our findings highlight the therapeutic relevance of B4GALT1 in PDAC, the feasibility of targeting aberrant glycosylation for anti-cancer therapy, and the translational potential of compound 1105486 as a new class of tumor-selective therapeutic agent for pancreatic cancer." (PMID 40860122, 2025).
acute myeloid leukemia (2 papers, 2020 to 2022). Acute myeloid leukemia (AML) is a group of neoplasms arising from precursor cells committed to the myeloid cell-line differentiation. "High expression of beta-1,4-galactosyltransferase 1 (B4GALT1) has been observed in several cancer types; however, its function in acute myeloid leukemia has rarely been studied." (PMID 36568388, 2022).
autoimmune disease (2 papers, 2017 to 2023). A disorder resulting from loss of function or tissue destruction of an organ or multiple organs, arising from humoral or cellular immune responses of the individual to their own tissue constituents. "Consistent with this idea, the B4GALT1 enhancer SVA insertion is linked to a genomic region implicated by GWAS in both inflammatory conditions and autoimmune diseases such as systemic lupus erythematosus and Crohn’s disease." (PMID 28824558, 2017).
clear cell renal cell carcinoma (2 papers, 2016 to 2020). "Here, we evaluate the association of B4GALT1 expression with oncologic outcome in patients with non-metastatic clear cell renal cell carcinoma (ccRCC)." (PMID 27092876, 2016).
fibrosis (2 papers, 2022 to 2025). the formation of excess fibrous connective tissue in an organ or tissue in a reparative or reactive process. "We then asked whether the increased expression of B4GALT1, observed in lung tissues affected by fibrosis, was a finding specific for the lung." (PMID 36499368, 2022). "Fibrosis and HCC: Our RNAseq analysis of the livers from Efcab4b−/− mice exhibit downregulation of the macrophage marker CD163, the CD44 antigen and Lymphocyte antigen 96 (Ly96) and upregulation of beta-1, 4-galactosyltransferase 1 (B4GALT1)." (PMID 40034259, 2025).
mastitis (2 papers, 2009 to 2022). Inflammation of breast tissue during lactation or postpartum due to an obstructed duct or infection. "Some positively selected genes were reported to be associated with lactation function and disease resistance, such as the butterfat rate [PPARGC1A], milk production [B4GALT1], immunity [IL2 and NFATC3], and mastitis resistance [ITSN2]." (PMID 35422847, 2022).
Obesity (2 papers, 2023). Accumulation of substantial excess body fat. "Examples of other protective variants include the N352S variant in B4GALT1 which is protective against cardiovascular disease and protein-truncating variants in GPR75 which reduce the risk of obesity, as well as the A88V variant in Gjb6, which protects against hearing loss in mice." (PMID 37163093, 2023).
prostate carcinoma (2 papers, 2022 to 2024). A carcinoma that arises from epithelial cells of the prostate gland. "B4GALT1 was identified as a unique tumor suppressor silenced by AKR1C3 activation, thereby facilitating castration-resistant prostate cancer progression." (PMID 39391236, 2024).
Thrombocytopenia (2 papers, 2020 to 2025). A reduction in the number of circulating thrombocytes. "Consistent with the severe thrombocytopenia, evidence supports hemorrhage at embryonic stage E14.5–E15.5 in B4galt1−/− fetuses." (PMID 31953383, 2020). "To distinguish whether the thrombocytopenia resulted from increased destruction of circulating platelets or from defective thrombopoiesis, we first measured the platelet half-life in adult B4galt1−/− and control mice." (PMID 31953383, 2020). "Notably, thrombocytopenia has also been described in various other types of CDG, including ALG1-, ALG8-, GALE-, GNE-, MPI-, PMM2-, and B4GALT1-CDG." (PMID 40613041, 2025). "Thus, the severe B4galt1−/− thrombocytopenia did not result from platelet destruction but reflected a primary failure in platelet formation." (PMID 31953383, 2020).
adenomyosis (1 paper, 2025). The growth of endometrial tissue inside the muscular wall of the uterine corpus. "At the molecular level, several enzymes involved in keratan sulfate biosynthesis were consistently upregulated in eutopic endometrium from adenomyosis patients, including B4GALT1, B3GNT2, CHST1, and CHST6." (PMID 41356013, 2025).
Arthritis (1 paper, 2022). Inflammation of a joint. "The activity of recombinant human galactosyltransferase B4GALT1 and ST6Gal1 on a single Fc fragment of IgG1 attenuated inflammation in a K/BxN arthritis model." (PMID 35370997, 2022).
autism (1 paper, 2009). Persistent deficits in social interaction and communication and interaction as well as a markedly restricted repertoire of activity and interest as well as repetitive patterns of behavior. "Inspection of the remaining genes in the non-complex-autism group CNVs revealed three additional genes functioning in the same processes (B4GALT1, ARSA, and GALNTL5), for which Prioritizer had determined borderline significance (0.057<nominal p-value<0.074)." (PMID 19492091, 2009).
cerebral infarction (1 paper, 2024). An ischemic condition of the brain, producing a persistent focal neurological deficit in the area of distribution of the cerebral arteries. "The alleviation of cerebral infarction by rh‐B4galt1 treatment was inhibited by TAZ siRNA and ML385, suggesting they could reverse the protective effects of rh‐B4galt1." (PMID 39233353, 2024).
Cerebral ischemia (1 paper, 2024). Restriction of arterial blood supply to the brain associated with insufficient oxygenation to support the metabolic requirements of the tissue. "We identified the potential molecular mechanisms of rh‐B4galt1 in cerebral ischemia using Western blotting." (PMID 39233353, 2024). "This study aims to investigate the function of β‐1,4‐galactosyltransferase 1 (B4galt1) in mouse brain ischemia/reperfusion (I/R) injury." (PMID 39233353, 2024). "However, it remains unclear whether rh‐B4galt1 regulates cerebral ischemia‐induced ferroptosis." (PMID 39233353, 2024).
colon cancer (1 paper, 2009). "In a blinded test performed in stool DNA from CRC patients, B4GALT1 and OSMR methylation were successfully detected with high frequency and thus have potential for identifying individuals with colon cancer." (PMID 19662090, 2009).
coronary artery disease (1 paper, 2022). "Similarly, rare deleterious variants in B4GALT1 have been linked to decreased coronary artery disease via reduction of fibrinogen and low-density lipoprotein cholesterol." (PMID 35761239, 2022).
COVID-19 (1 paper, 2021). A disease caused by infection with severe acute respiratory syndrome coronavirus 2.
Hepatic steatosis (1 paper, 2026). Steatosis is a term used to denote lipid accumulation within hepatocytes. "Hepatocyte-specific B4galt1-knockout mice exhibited significantly attenuated hepatic steatosis and inflammation, but not fibrosis." (PMID 41860570, 2026).
hepatopathy (1 paper, 2023). "B4GALT1 is highly expressed in the liver, and patients with mutations in B4GALT1 exhibit hepatopathy." (PMID 37907465, 2023). "It has been reported that the phenotype of patients with mutation in B4GALT1 includes inherited coagulation disturbances with hepatopathy and hepatomegaly." (PMID 37907465, 2023).
infarct (1 paper, 2024). "We demonstrated that rh‐B4galt1 markedly improved neurological function, reduced cerebral infarct volume and preserved the completeness of blood–brain barrier (BBB) for preventing damage." (PMID 39233353, 2024).
ischemia (1 paper, 2024). A hypoperfusion of the BLOOD through an organ or tissue caused by a PATHOLOGIC CONSTRICTION or obstruction of its BLOOD VESSELS, or an absence of BLOOD CIRCULATION. "In summary, rh‐B4galt1 can inhibit the degradation of TJPs, thereby alleviating ischemia‐induced BBB damage." (PMID 39233353, 2024). "In a word, the neuroprotective function of rh‐B4galt1 in ischemia‐induced brain damage has relationship with TAZ/Nrf2/HO‐1 pathway." (PMID 39233353, 2024). "Rh‐B4galt1 exerts neuroprotective effects by regulating ischemia‐induced ferroptosis, which is mainly dependent on the heightening of the TAZ/Nrf2/HO‐1 pathway." (PMID 39233353, 2024).
ischemic stroke (1 paper, 2024). A stroke disorder caused by obstruction of blood flow to the brain, due to thrombotic (local blood clot formation) or embolic (due to a blood clot or other material traveling from another site) event. "The underlying mechanisms need to be further revealed before rh‐B4galt1 could be used for the treatment of ischemic stroke." (PMID 39233353, 2024). "The mechanisms by which B4galt1 participates in the progression of ischemic stroke need to be further investigated." (PMID 39233353, 2024). "In the present research, we constructed a mouse ischemic stroke model using the MCAO method to explore the role of B4galt1 in cerebral ischemic injury." (PMID 39233353, 2024). "As a result, B4galt1 may be regarded to be a possible substance in treating ischemic stroke." (PMID 39233353, 2024). "Thus, B4galt1 could be seen as a promising novel objective for ischemic stroke therapy." (PMID 39233353, 2024). "Thus, B4galt1 may be considered a novel potential therapeutic target for ischemic stroke treatment." (PMID 39233353, 2024). "In our study, we found that rh‐B4galt1 reduced BBB extravasation and improved vascular reperfusion 24 h after ischemic stroke, but the exact mechanism remains unclear." (PMID 39233353, 2024).
liver cancer (1 paper, 2023). An epithelial or non-epithelial malignant neoplasm that arises from the liver. "However, the role of B4GALT1 in liver cancer remains unclear." (PMID 37907465, 2023).
liver disorder (1 paper, 2022). A disease involving the liver. "Differently, B4GALT1-deficient mice and CD19-cre B4GALT1-floxed mice showed reduced tumor nodules and liver disorders after cancer induction." (PMID 35267641, 2022).
melanoma (1 paper, 2022). A malignant, usually aggressive tumor composed of atypical, neoplastic melanocytes. "Here, based on qPCR data for B4GalT1–B4GalT7 transcripts in melanocytes and melanoma cells, we show how to perform the analysis step by step, and how to solve problems using this new methodological approach." (PMID 35228606, 2022).
myocardial infarction (1 paper, 2019). Gross necrosis of the myocardium, as a result of interruption of the blood supply to the area, as in coronary thrombosis. "For example, BC166504 co-expresses with 4 mRNAs involved in myocardial infarction: B4galt1, Eln, Il1b and Nfkbiz." (PMID 31827539, 2019). "In the co-expression network, we found 16 genes directly involved in myocardial infarction, including Alox5ap, Itgb2 and B4galt1." (PMID 31827539, 2019).
ovarian carcinoma (1 paper, 2021). A malignant neoplasm originating from the surface ovarian epithelium. "Moreover, the first member of B4GALT family, B4GALT1 has been partially studied in ovarian cancer invasion and metastasis." (PMID 33663405, 2021).
psoriasis (1 paper, 2022). An autoimmune condition characterized by red, well-delineated plaques with silvery scales that are usually on the extensor surfaces and scalp. "Furthermore, a comparison of the levels of the enzymes in AD vs psoriatic epidermis suggested a degree of disease-specificity, with B4GALT1, FUT4 and ST6GAL1 found expressed at levels significantly higher than in psoriasis." (PMID 35784319, 2022).
thyroid cancer (1 paper, 2025). "Notably, genes such as B4GALT1, ALDH1A1, NDUFV2, and ACO1 had mutations in 6% of samples, making them frequent mutational targets in thyroid cancer." (PMID 40861812, 2025).
triple-negative breast carcinoma (1 paper, 2022). An invasive breast carcinoma which is negative for expression of estrogen receptor (ER), progesterone receptor (PR), and human epidermal growth factor receptor 2 (HER2). "The latest study report shows that B4GALT1 is a newly discovered PD-L1 glycosyltransferase, and in triple-negative breast cancer, RBMS1 can bind to the 3′-UTR of B4GALT1 to stabilize its mRNA." (PMID 36568388, 2022).
type 1 diabetes (1 paper, 2018). "Next, we discovered eight gene polymorphisms (ORMDL3, SPHK2, B4GALNT1, SLC1A5, GALC, PPARD, PPARG and B4GALT1) involved in sphingolipid metabolism that contribute to the genetic predisposition to type 1 diabetes." (PMID 29671030, 2018). "The changed expression of B3GALT5, B3GALT4 and B4GALT1 suggest that the development of type 1 diabetes is associated with changes in the composition of islet glycosphingolipids with increases in the neolacto/lacto series and decreased levels of gangliosides." (PMID 29671030, 2018). "For six genes (ORMDL3, GALC, SPHK2, SLC1A5, PPARD and B4GALT1) the SNPs with the strongest association with type 1 diabetes (lowest p value) also acted as cis-eQTLs, suggesting that these SNPs regulate the expression of their associated genes." (PMID 29671030, 2018).
tumor (26 papers, 2009 to 2026). "Taken together, our results suggest that B4GALT1 is significantly downregulated in HCC tissue compared with its adjacent non-tumor tissue and that low B4GALT1 expression is associated with poor overall survival of patients with HCC." (PMID 37907465, 2023). "Tumour samples were harvested for further analysis at the end of the treatment, and IHC staining and flow cytometry analysis showed that B4galt1 deficiency significantly decreased PD-L1 level and increased CD8 + T-cell and CD8 + GZMB + cell densities." (PMID 37303063, 2023). "The CD19-cre B4GALT1-floxed mice and B4GALT1-deficient mice developed much smaller tumors and showed less tumor burden than the WT mice." (PMID 35267641, 2022). "In a previous study, we demonstrated that the expression of B4GALT1 was linked to tumor development and progression." (PMID 36499368, 2022). "B4GALT1 expression was significantly associated with tumor T stage (P < 0.001 and P < 0.001, respectively) and Fuhrman grade (P<0.001 and P<0.001, respectively) and necrosis (P=0.021 and P=0.002, respectively) in the training cohort and validation cohort." (PMID 27092876, 2016). "B4GALT1 expression was significantly associated with tumor T stage (P<0.001 and P<0.001, respectively), Fuhrman grade (P<0.001 and P<0.001, respectively) and necrosis (P=0.021 and P=0.002, respectively) in both training and validation cohorts." (PMID 27092876, 2016). "High B4GALT1 expression was positively associated with histologic necrosis status, tumor T stage and Fuhrman grade, which strong indicated that B4GALT1 plays a critical role in ccRCC development and progression." (PMID 27092876, 2016). "Finally, the expression levels of B4GALT1 normalized to tumor-infiltrated CD8+ T-cells in tumor microenvironment are significant and negatively associated with prognosis of human patients." (PMID 41860948, 2026). "For instance, hypermethylation of CpG islands within the B4GALT1 promoter may contribute to transcriptional repression and reduced B4GALT1 expression, leading to altered glycosylation profiles associated with tumor progression and therapeutic resistance." (PMID 38562924, 2024). "B4GALT1 participates in the formation of N-glycosylation by transferring β-1,4-chain galactose to acceptor sugars, and accumulating evidence has implicated this protein in tumour biology and progression." (PMID 37303063, 2023). "Our results reveal the important roles of protein N-glycosylation in regulating functions of CD8+ T-cells and prove that B4GALT1 is a potential target for tumor immunotherapy." (PMID 41860948, 2026). "In PDAC, both proteomic and transcriptomic analyses demonstrate that B4GALT1 is frequently overexpressed in tumor tissues relative to the normal pancreas." (PMID 40860122, 2025). "Recent cancer studies have revealed that aberrant expression or hyperactivity of B4GALT1 can reshape the glycosylation landscape of tumor cells, driving oncogenic phenotypes such as increased invasiveness, metastasis, and immune evasion." (PMID 40860122, 2025). "To this end, we observed that the expression of both SLC2A1 and B4GALT1 was enriched in tumor tissue regions in the EC." (PMID 38517922, 2024). "The survival plot compares the overall survival (OS) (A) and the disease-free survival (DFS) (B) between tumor samples with high B4GALT1 expression (n = 89) and low B4GALT1 expression (n = 89)." (PMID 38608280, 2024). "Survival plots revealed a significant decrease in overall survival (OS) and disease-free survival (DFS) among tumor samples exhibiting elevated GOLM1 or B4GALT1 expression (n = 89) compared with those with low expression (n = 89)." (PMID 38608280, 2024). "The boxplot analysis revealed a statistically significant increase in GOLM1 and B4GALT1 expression in the tumor samples as compared with the normal control group." (PMID 38608280, 2024).